CCL17 (C-C motif chemokine ligand 17)
Diseases named in the same sentence as CCL17 in open-access papers (continued):
Sharing a sentence is not in itself a finding about the gene and the disease.
COVID-19 (21 papers, 2020 to 2025). A disease caused by infection with severe acute respiratory syndrome coronavirus 2. "Other potential mechanisms of the RC decoction against the ALI involved the pathways of ribosome and coronavirus disease 2019 (COVID-19); the target genes of inflammatory factors, such as Ccl17, Cxcl17, Cd163, Cxcr5, and Il31ra, and lncRNAs; and the regulations of the respiratory cilia." (PMID 36072401, 2022). "The figure shows lower expression levels of CCL22 and CCL17 in high-severity COVID-19 samples compared to mild and moderate samples." (PMID 40362649, 2025). "A total of 13/124 measures including CCL5, CCL17, IL-18, IFNα2, Fractalkine, classical monocytes, T cells, and CD4Temra exhibited significant sex differences in female vs. male COVID-19 patients." (PMID 37998327, 2023). "Repeating the analysis to only include first samples, showed again increased levels of CXCL9 and CCL20 in severe disease, but also increased levels of CXCL10 and a downregulation of CCL17 in patients with severe COVID-19." (PMID 34957382, 2022). "A lower expression of CCL17 was particularly pronounced in severe COVID-19 sufferers, while the predictive capacity of CCL17 was indicated in confirmed cases of COVID-19." (PMID 36016187, 2022). "Other potential mechanisms involved the ribosome and COVID-19 pathways; the inflammatory factors genes, such as Ccl17, Cxcl17, Cd163, Cxcr5, and Il31ra, and the lncRNAs genes; and the respiratory cilia functions." (PMID 36072401, 2022). "In contrast, levels of CCL17 (also known as TARC) and CCL22 (also known as MDC) were reduced in COVID-19 patients relative to HVs, with an inverse association observed between CCL22, but not CCL17, levels and COVID-19 severity." (PMID 33232303, 2021). "At an early phase of infection, patients with low CCL17 levels subsequently developed severe/critical COVID-19, whereas patients with comparatively higher CCL17 levels developed mild to moderate disease." (PMID 33613280, 2020). "Moreover, this class of oxylipins was the only one to consistently exhibit positive correlations with the chemokine CCL17, a T cell development inducer (part of the adaptive immune response) that is downregulated in COVID-19." (PMID 35888743, 2022). "Serum CCL17 levels have been suggested as a prognostic marker for severe cases of COVID-19." (PMID 33613280, 2020). "In female COVID-19 patients, levels of IFN-α2, CCL17, Fractalkine, CD4Temra, and naïve CD8 T cells were higher than in male COVID-19 patients." (PMID 37998327, 2023). "We identified upregulation of several NFκB pathway components (NFKB2 and NFKBIA) and inflammatory cytokines (CXCL9, CCL17, and CCL21) in the presence of viral transcripts, in line with the abundant literature describing these molecules in the early steps of COVID-19 pathogenesis." (PMID 37858234, 2023). "TARC/CCL17 concentrations and CC16 protein levels were measured in serum samples of 20 patients without and in 173 patients with a proven COVID-19 RT-PCR positive test." (PMID 40236699, 2025). "We observed lower TARC/CCL17 concentrations in COVID-19 positive patients (median serum levels are 124.4 pg/mL in the non ICU admitted patient group, and 131.7 pg/mL in the ICU admitted patient group) compared to COVID-19 negative patients (median 301.3 pg/mL) (p = 0.002)." (PMID 40236699, 2025).
hepatocellular carcinoma (18 papers, 2017 to 2025). A malignant tumor that arises from hepatocytes. "Activated macrophages (M2) secreted chemokines, such as chemokine ligand 17 (CCL17), whose expression was significantly associated with clinical pathological characteristics of hepatocellular carcinoma and with poorer overall survival rates." (PMID 34745015, 2021). "CCL2+CCL17+ TANs correlated with tumor size, differentiation, stage, vascular invasion, and poor prognosis in hepatocellular carcinoma patients." (PMID 39061147, 2024). "A murine study of hepatocellular carcinoma indicated that T-regulatory cells are attracted by CCL17 through the CCR4 axis and that high CCR4 expression is positively associated with metastasis." (PMID 37686617, 2023). "The authors suggested that the Wnt/β-catenin pathway downstream of CCL17/CCR4 signaling regulated the stemness of hepatocellular carcinoma cells." (PMID 36118530, 2022). "The CCL17/C-C chemokine receptor 4 (CCR4) axis has been recently reported to induce the migration of hepatocellular carcinoma cells 17 and enhance epithelial-mesenchymal transition (EMT) in breast cancer via Akt signaling." (PMID 33664865, 2021). "CCL17 high expression in tumor cells predicts poor survival in patients with hepatocellular carcinoma." (PMID 28178948, 2017). "Currently, there is no clinical study showing a correlation of CCL17 with the outcome of NSCLC patients but in other cancers, a high number of CCL17+ TANs within the tumor was correlated with a worse prognosis and tumor progression in hepatocellular carcinoma patients." (PMID 39061147, 2024). "In mouse models, TANs mediate the infiltration of regulatory T (Treg) cells and macrophages in the TME by secreting the chemokines CCL2 and CCL17, leading to the growth of hepatocellular carcinoma cells and increasing the resistance of hepatocellular carcinoma patients to sorafenib." (PMID 36324574, 2022). "CCR4 and its ligands CCL17 and CCL22 have been shown to mediate stimulatory signals for angiogenesis and tumor growth, and CCR4 blockade was associated with reduced tumor invasion and metastasis and better prognosis in some human cancer types such as hepatoma and colon cancer." (PMID 37124725, 2023). "Notably, co-implantation of hepatocellular carcinoma cells with M2 macrophages significantly increased tumor growth in a mouse xenograft model compared to co-implantation with other types of cells, indicating that CCL17 can drive tumorigenicity." (PMID 36118530, 2022). "Abundant evidences indicate that CCL17 can perform biological functions through interacting with CCR4 in a series of diseases, including tumor-promoting effects on hepatocellular carcinoma and bladder cancer." (PMID 39473097, 2025). "Sorafenib is a treatment for hepatocellular carcinoma (HCC) that enhances its anticancer effects by inhibiting CCL2 and CCL17 transcriptional regulators in neutrophils." (PMID 41451221, 2025). "Hepatocellular carcinoma cells express high levels of CCR4 153, and treating these cells with either the conditioned medium from M2 macrophages, which express higher CCL17 levels than M1 macrophages, or with exogenous CCL17, promoted survival, migration, and tumorsphere formation." (PMID 36118530, 2022). "It was highlighted that TANs, but not circulating neutrophils, via the production of CCL2 and CCL17 and the recruitment of monocytes and Treg cells, were the cause of the refractoriness to sorafenib, the first line treatment for hepatocellular carcinomas (HCC)." (PMID 35664746, 2022). "Consistently, in human hepatocellular carcinoma tissues, TANs expressed abundantly CCL17 and CCL2, which could attract Tregs and macrophages, respectively, and depletion of neutrophils enhanced the sensitivity to sorafenib in mouse HCC models, as evidenced by reduced tumor growth." (PMID 32422991, 2020).
hepatocellular carcinoma (continued). "In L929 mouse fibroblasts, chronic hypoxia reduces CCL17/TARC expression, while in human hepatoma cells and lung adenocarcinoma cells, chronic hypoxia does not affect CCL17/TARC expression." (PMID 32781743, 2020).
psoriasis (17 papers, 2010 to 2025). An autoimmune condition characterized by red, well-delineated plaques with silvery scales that are usually on the extensor surfaces and scalp. "The strong expression of CCL17 in psoriasis skins were also reflected by immunofluorescence that showed intense CCL17 staining in dermal microvessels." (PMID 29066845, 2017). "Our data showed that serum from psoriasis patients or TNF-α promoted the protein expression of CCL17 and CCL22 in HUVECs while serum from normal in culture medium silenced the expression of these chemokines." (PMID 29066845, 2017). "Namely, RHCG, TCN1, KLK6, and LCN2 were chosen for psoriasis and CCL17, NCF4, BATF3, and CLEC4G as ACD-specific genes." (PMID 25058585, 2014). "Moreover, ligands for CCR4—CCL17 and CCL22, and CCR10—CCL27 have been associated with AD, psoriasis, cutaneous lymphomas, and systemic sclerosis." (PMID 37371632, 2023). "The heatmap showed that C–C motif chemokine ligands (Ccl3, Ccl4, Ccl5, Ccl17, Ccl19-Ps2, and Ccl22) were expressed at higher levels in IMQ-induced psoriasis." (PMID 38566145, 2024). "In AD patients, TARC/CCL17 levels are significantly higher than those of healthy control subjects and patients with psoriasis." (PMID 23282416, 2010). "Besides, IRF4+ cDC2 cluster that displays an elevated expression of CCL17, CCL22, and a population of fibroblasts that expressed CCL19 and BAFF were reported in psoriasis biopsies." (PMID 34777377, 2021). "Across five patients with psoriasis, we reported a sub-cluster of DCs (IRF4+ cDC2) that displays elevated expression of CCL17, CCL22, and IL12B, markers of cDC2s that have recently been shown to drive psoriatic inflammation in mice and humans through the recruitment of inflammatory T cells." (PMID 33053333, 2020). "Furthermore, the TNF- α treatment exhibited enhancement effect on mRNA expression of CCL17, CCL22 in HUVECs, which was similar to psoriasis sera." (PMID 29066845, 2017). "We confirmed that endogenous TWEAK was required for maximal expression of CCL2, CCL5 and CCL7, and furthermore, we found defective production of CCL17 and CCL20 in mice lacking TWEAK in the AD model and the psoriasis model, respectively." (PMID 28530223, 2017).
allergic asthma (16 papers, 2015 to 2025). A asthma with a basis in a pathological type I hypersensitivity reaction. "The Th2 cytokines that play an important role in allergic asthma, like IL-5, IL-13, CCL17, and IL-33 along with total IgE in serum were measured." (PMID 32582180, 2020). "Similarly, increased CCL17 levels have been previously reported in the serum of patients with allergic asthma, while CCL17 levels were unaltered in patients with allergic rhinitis." (PMID 40181810, 2025). "More importantly, accumulating evidence reveals that in allergic asthma, M2 macrophages release high levels of chemokines, including CCL-17 and CCL-22, resulting in the recruitment of Th2 cells and amplification of polarized Th2 cell responses in the bronchial tissue." (PMID 37957139, 2023). "In an experimental animal model of allergic asthma, exposure to cigarette smoke induced CCL17/TARC production and secretion in macrophages from bronchial lavage, evidence that smoke exposure appears to be causing the increase in CCL17/TARC." (PMID 34771561, 2021). "Also, we recommend selective suppression of pathogenic M2a proteins e.g. TGM2, CCL17/CCL22, TGF-β1, and murine Arg1, FIZZ1 and CHI3L3, for the future developments of effective therapies for allergic asthma." (PMID 32024540, 2020). "Also, CCL17 and CCL22 induce naïve T cell differentiation into Th2 cells, indicating the pathogenic role of CCL17 and CCL22 in allergic asthma." (PMID 32024540, 2020). "In conclusion, the data from this study demonstrate for the first time that compound 8a as a small molecule antagonist specifically targeting CCR4/CCL17/CCL22/CKLF1 axes effectively attenuates the allergic airways inflammation in a murine model of allergic asthma in vivo." (PMID 29118379, 2017). "CD11b+ DCs are primary sources of type 2 chemokines CCL17 and CCL22, which recruit Th2 cells to the airways in allergic asthma, thus contributing to Th2 inflammation." (PMID 40405264, 2025). "Since CCL17 and CCL22 are involved in the pathogenesis of atopic diseases, we finally studied the in vivo activity of GPN279 and GPN136 at inhibiting inflammatory cell recruitment in a mouse model of allergic asthma." (PMID 26442456, 2015). "Of these, only CCL17 (chemokine that specifically binds and induces chemotaxis in T cells via CCR4) displayed a higher non-specific relationship with allergic asthma when compared to the value obtained for non-allergic asthma." (PMID 33936056, 2021).
inflammatory skin disease (12 papers, 2015 to 2025). Inflammatory skin disorders covers a broad category that includes many conditions ranging in severity, from mild itching to grave medical health complications These disorders are common in people of all ages and races. "In the context of inflammatory skin diseases, CCL17/TARC and CCL22/MDC production is increased epidermal keratinocytes upon stimulation with TNF-α/IFN-γ, resulting infiltration of immune cells into the lesion area." (PMID 36793948, 2023). "Likewise, several chemokines, CCL3L1, CCL17, CXCL2, and selectin SELPLG, were upregulated at week 8 in CS and have been implicated in various inflammatory skin diseases." (PMID 34925353, 2021). "CCL17 and CCL18 are chemokines that are significantly involved in T cell–mediated reactions and characteristic for various inflammatory skin diseases with TH2 dominance." (PMID 34925353, 2021). "AD is a Th2-dominant inflammatory skin disease and an abnormal expression of Th2 chemokines such as TARC/CCL17 (thymus and activation-regulated chemokine) and MDC/CCL22 (macrophage-derived chemokine) in keratinocytes were observed at the inflammatory site of epidermis." (PMID 37239060, 2023). "Therefore, the downregulation of RANTES/CCL5, TARC/CCL17, and MDC/CCL22 in keratinocytes may be a potential target for treating inflammatory skin diseases." (PMID 30642008, 2019).
Arthritis (11 papers, 2018 to 2025). Inflammation of a joint. "In the present study, using mostly Il23p19-deficient (Il23p19−/−) mice, we demonstrate that similar to TNF, GM-CSF, and CCL17, IL-23 is also required for the development of zymosan-induced arthritis (ZIA) and its associated inflammatory pain-like behaviour (herein referred to as pain)." (PMID 32471485, 2020). "Prior work implicated TNF, GM-CSF and CCL17 in the progression of ZIA pain and disease, while Il23p19−/− mice were protected from acute T- and B-lymphocyte independent arthritis induced by recombinant TNF, GM-CSF or CCL17." (PMID 39107827, 2024). "Another study proved that the expression of CCL17 during the inflammatory reaction of the peritoneum and lung was mainly regulated by GM-CSF and emphasized the role of CCL17 in driving the pain and disease progression of arthritis." (PMID 35887379, 2022). "Evidence of CCL17 contributing to pain responses via CCR4 predominantly comes from murine models of arthritis, demonstrating that CCL17 can drive arthritic pain and may contribute significantly to the development of chronic pain." (PMID 41291326, 2025). "We found here that systemically administered IL-23 could elicit pain and arthritis in a mBSA-injected joint and that neutralization of TNF and deletion of Csf2 and Ccl17 prevented the pain and reduced the associated arthritis." (PMID 39107827, 2024). "It is perhaps worth noting that in two T- and B-lymphocyte-independent arthritis models in which IL-23 is induced or systemically administered there appears to be an association with the same cytokines, namely, TNF, GM-CSF and CCL17, in controlling pain and disease." (PMID 39107827, 2024). "The role of IL-23 in the development of pain-like behaviour was investigated using mouse arthritis models (zymosan-induced arthritis and GM-CSF-, TNF-, and CCL17-driven monoarticular arthritis) and inflammatory pain models (intraplantar zymosan, GM-CSF, TNF, and CCL17)." (PMID 32471485, 2020). "Even though TNF and GM-CSF are not required in this model, interestingly, arthritic pain was again not seen in Il23p19−/− mice; as measured histologically, Il23p19−/− mice were also protected from CCL17-driven arthritis development (P = 0.0002, 95% CI 1.501, 5.332)." (PMID 32471485, 2020). "ZIA, induced by an intra-articular (i.a.)injection of zymosan, is a widely used macrophage-dependent, monoarticular arthritis model; we have previously reported that endogenous GM-CSF, TNF, and CCL17 are required for pain and optimal arthritis development in this model." (PMID 32471485, 2020). "Similarly, it was found that CCL17-deficient mice with induced arthritis did not develop pain after joint injury, suggesting that CCL17 is required for the genesis of arthritis pain." (PMID 41291326, 2025). "We note that the GM-CSF–CCL17 signaling axis can be downstream of TNF and that CCL17 has recently been postulated as a therapeutic target in other forms of arthritis." (PMID 32765525, 2020). "We have also reported that both GM-CSF-driven inflammatory pain and arthritis models (using exogenous GM-CSF), and GM-CSF-dependent inflammatory pain and arthritis models (e.g. zymosan-induced arthritis (ZIA)) are dependent on IRF4 and CCL17, and on TNF." (PMID 29622035, 2018). "In murine models of arthritis, GM‐CSF up‐regulated IRF4 and thus CCL17 production by enhancing the expression of the epigenetic enzyme JMJD3 demethylase, which activates IRF4 expression." (PMID 29315512, 2018). "Also, using a new IL-23-driven arthritis model, we present data for a dependence on TNF, GM-CSF and CCL17 for pain and disease reinforcing their links with IL-23 in inflammation-associated pain and disease, as exemplified here in joints." (PMID 39107827, 2024). "Utilizing several inflammatory models of arthritis, we have demonstrated that CCL17 has a non-redundant role in mediating arthritic pain-like behavior and disease." (PMID 37860753, 2023).
colitis (10 papers, 2018 to 2025). Inflammation of the colon. "It has been found that the high level of CCL17 in human serum is related to the high risk of cardiovascular diseases, and studies in mice show that CCL17 has pro-inflammatory effects in AS and colitis." (PMID 41266856, 2025). "Inhibition of CCL17 by peptides, antibodies, or small molecules is an exciting new therapeutic approach to test on animal colitis models." (PMID 30037025, 2018). "Competitive inhibition of CCL17 by peptides is a new therapeutic approach to test on animal colitis models." (PMID 30037025, 2018). "While CCL5 and CXCL11 are good therapeutic chemokine candidates to be exogenously administered, CCL17 is a good candidate chemokine to competitively inhibit or limit colitis pathology." (PMID 30037025, 2018). "After 7 days of induced colitis, upregulation of the expression of 22 genes (Ccl2, Ccl3, Ccl4, Ccl5, Ccl6, Ccl7, Ccl12, Ccl17, Cxcl1, Cxcl2, Cxcl6, Cxcl9, Cxcl11, Ccr1, Ccr2, Ccr3, Ccr5, Ccr8, Cxcr2, Csf3, Osm, and Spp1) was observed in the CβG− group compared to the HβG- control group." (PMID 35163326, 2022). "Interestingly, oxazolone colitis was the only dataset in which Ccl17 was significantly regulated." (PMID 34136502, 2021). "CCL17 is increased in the inflamed mucosa of murine colitis, and CCL17-deficient animals are protected from colitis induced by DSS,103 although the ability of mice lacking CCR4+ T-cells to develop florid colitis suggests contribution by CCR4+ innate effector cell types." (PMID 30137309, 2018). "Evidence also shows that C‐C motif ligand 17 (CCL17), the chemokine ligand of CCR4 is required to induce colitis in mice." (PMID 39678631, 2024). "Our analysis resulted in identifying three new therapeutic targets towards ameliorating colitis: CCL5, CXCL11, and CCL17." (PMID 30037025, 2018).